ALB (albumin)
Diseases named in the same sentence as ALB in open-access papers (continued):
Sharing a sentence is not in itself a finding about the gene and the disease.
COVID-19 (continued). "Indeed, native albumin concentrations similar to those found in patients with normoalbuminemia (3.5 g/dL) markedly bound the COVID-19 spike protein S1 subunit, and this binding was drastically reduced by decreasing native albumin concentrations to 1 g/dL." (PMID 35160039, 2022). "Interestingly, several works have reported a potential relationship between decreased serum albumin levels and COVID-19 infection, due to the inflammatory response in COVID-19 patients." (PMID 35160039, 2022). "However, only 39.1% of COVID-19 patients showing on-admission albumin levels < 2.5 g/dL were discharged alive." (PMID 35160039, 2022). "In this regard, from a clinical point of view, the present results may suggest that, depending on the albumin levels on admission, a more aggressive therapy against COVID-19 may be considered at the beginning of hospitalization." (PMID 35160039, 2022). "Given the strong prognostic value of low serum vitamin D and low serum albumin on COVID-19 outcomes, we aimed to investigate the potential of combining serum vitamin D and albumin levels to increase the predictive power of the single tests in adults affected by COVID-19 pneumonia." (PMID 35182287, 2022). "ALB was significantly related to the outcomes of patients with COVID-19 and depended on many factors.The deceased levels of ALB may be explained by the persistent inflammatory response, making the production decreased and consumption increased." (PMID 36619759, 2022). "Similarly, in our study, low serum albumin levels were observed in severe COVID-19 patients, and statistical significance was determined between the groups." (PMID 35950826, 2022). "The current opinion aims the research community the application of Site-Directed Spin Labeling Electron Paramagnetic Resonance spectroscopy (SDSL-EPR) and 3-Maleimido-PROXYL radical in determining abnormalities of the albumin dynamics and protein concentrations in COVID-19 critical patients." (PMID 36552520, 2022). "An interesting observation, that evidently requires further investigation, was that the recombinant receptor-binding region, RBD, of the COVID-19 spike protein S1 subunit containing the S1 subunit amino-acid sequence from 319 to 541, also bound to native albumin." (PMID 35160039, 2022). "Moreover, with increased COVID-19 severity in hospitalized patients, increased levels of ischemia-modified albumin were observed." (PMID 36009328, 2022). "The low molecular weight fraction of 5% human serum albumin commercial preparation (AMP5A) is a novel biologic drug currently under clinical investigation for the treatment of osteoarthritis and the hyperinflammatory response associated with COVID-19." (PMID 35261923, 2022). "In addition, pneumonia was detected in the COVID-19-associated MRSA (COVID-MRSA) that showed decreased levels of lymphocytes and albumin and increased the mortality rate from 2.3% to 25.23%." (PMID 35997388, 2022). "Furthermore, higher neutrophil rates (64.9% vs. 73.8%), lower lymphocyte counts (21.4% vs. 14%), and lower albumin levels (32.5 g/l vs. 21.6 g/l) at COVID-19 diagnosis were observed in patients who died due to COVID-19." (PMID 35171337, 2022). "The hypocalcemia observed during the acute COVID-19 was reported to be independent of vitamin D deficiency, albumin levels, and disease severity." (PMID 36561720, 2022). "In our study, we found that COVID-19 patients with GI symptoms or elevation of liver enzymes experienced severer clinical course, with a higher rate of severe type of disease, lower blood hemoglobin and albumin, and longer disease duration." (PMID 36341271, 2022). "Albumin was slightly lower in the patients with severe COVID-19." (PMID 35566453, 2022). "Overall, whether albumin administration to patients with COVID-19 is beneficial, is currently unknown." (PMID 35736249, 2022). "A decrease in the number of albumin, platelet, lymphocytes may be a guide in determining the severity of COVID-19." (PMID 35950826, 2022).
COVID-19 (continued). "In conclusion, the early evaluation of albumin levels and liver-related parameters may be indispensable tools for the early assessment of the clinical course of patients with COVID-19." (PMID 35956107, 2022). "Furthermore, we found an association of low albumin levels and LOS, which was not only observed in patients with COVID-19." (PMID 36014955, 2022). "In terms of laboratory parameters, when comparing children with COVID-19 with the control group, COVID-19 cases tended to have higher hemoglobin and albumin but lower white cell count—specifically, neutrophil count, total bilirubin, aspartate aminotransferase, and alanine aminotransferase." (PMID 35168193, 2022). "In conclusion, derived laboratory biomarkers such as the De Ritis ratio, CRP-to-albumin ratio, LDH-to-hemoglobin ratio, CRP-to-lymphocyte ratio, and LDH-to-albumin ratio show significant association with all-cause mortality in KTR with COVID-19, suggesting their potential risk stratification role." (PMID 36556433, 2022). "Receiver operating characteristic analyses were performed to determine the area under the curve (AUC), optimal cut-off value, sensitivity and specificity values of age, ADMA, SDMA, L-NMMA, NLR, CRP, D-dimer, fibrinogen, ferritin, total protein, albumin in correlation with COVID-19 severity." (PMID 36627978, 2022). "Interestingly, pre-binding LA to albumin normalized the unbound FA elevation and reversed the severe COVID-19 like phenotype induced by LA." (PMID 35502320, 2022). "On ROC analysis, urea was fair (AUC=0.721), creatinine (AUC=0.698) and IL-6 (AUC=0.698) were acceptable predictors of mortality, while albumin (AUC=0.698) was an acceptable predictor of survival in severely ill COVID-19 patients during their intensive care stay." (PMID 36185918, 2022). "We also observe protective associations between the genetic underpinnings of COVID-19 severity and that of non-smoking, serum albumin, apolipoprotein A, HDL cholesterol level, and several nutrients." (PMID 35115602, 2022). "Furthermore, regarding COVID-19, low levels of nutritional status biomarkers (such as albumin, pre-albumin, lymphocyte) are correlated with poorer outcomes." (PMID 35684113, 2022). "Lymphocyte, monocyte count and albumin level were in negative linear association with COVID-19 severity." (PMID 35075140, 2022). "Furthermore, in COVID-19, LDH levels are positively associated with systemic inflammation, and high LDH and low albumin have been reported as predictors of poor prognosis in HD patients with COVID-19." (PMID 35615622, 2022). "The purpose of this study is to evaluate whether admission albumin levels reliably predict outcomes in COVID-19 patients." (PMID 33725003, 2021). "Stepwise linear regression analysis of continuous variables showed four variables such as direct bilirubin (p = 0.001), low albumin (p = 0.013), increased respiratory rate (0.002), and raised WBC count (<0.001), which were independently associated with increased COVID-19-related mortality." (PMID 34055545, 2021). "Low albumin level can help to early recognition of severe COVID-19." (PMID 33853568, 2021). "Low albumin levels, high C-reactive protein levels, a high leukocyte count, and low lactate dehydrogenase levels make the model more likely to predict a critical/severe COVID-19 case." (PMID 33534723, 2021). "Therefore, we conducted this study to further evaluate the significance of serum albumin levels on admission and other factors concerning morbidity and mortality of hospitalized patients with COVID-19." (PMID 34367693, 2021). "Twenty-nine consecutive patients with COVID-19 PCR positivity, pneumonia, and a D-dimer plasma level above 1 microgram/mL and albumin serum levels < 3.5 g/dL were divided into two groups: 10 patients were treated with albumin infusions for 7 days, while 19 patients served as controls." (PMID 34281177, 2021).
COVID-19 (continued). "In COVID-19, interaction of albumin with bioactive lipid mediators may play a particular role in the occurrence of cytokine storm and organ failure." (PMID 33925831, 2021). "For example, the decrease in Albumin levels during COVID-19 was matched with the increase in polymorphonuclear myeloid-derived suppressor cells (PMN-MDSC); total T-cell abundance was related to the fraction of medium size HDL, where both variables decrease with COVID-19 severity." (PMID 35095900, 2021). "Serum albumin, prealbumin, oxygenation index, and LDH were risk factors of COVID-19." (PMID 34327212, 2021). "Likewise, the CRP-to-albumin ratio (CAR) can predict mortality in COVID-19 patients with an AUROC of 0.807." (PMID 34683480, 2021). "In previous studies, liver function tests in individuals with COVID-19 revealed mixed findings: serum albumin levels are reduced; total bilirubin, alanine aminotransferase and aspartate aminotransferase levels are elevated while prothrombin time and partial thromboplastin time are shortened." (PMID 34441048, 2021). "Since the albumin-coated NPs could be targeted via a damaged endothelial glycocalyx in COVID-19 patients, we think that the described injectable BSA-Zein-NIC formulation will be very advantageous." (PMID 34300711, 2021). "Furthermore, the levels of inflammatory markers (CRP, d-dimer and neutrophil-to-leukocyte ratio), creatinine level and AST level were higher and albumin levels were lower in the COVID-19-positive group than in the COVID-19-negative group." (PMID 34190873, 2021). "Also, the higher values of the neutrophil count, CRP, D dimer, PCT, LDH, urea, creatinine, CK, Ferritin, TBIL, AST, as well as lower values of lymphocyte and monocyte count, and albumin were detected in the group of patients with severe COVID-19." (PMID 34917631, 2021). "We observed that prenatal low albumin and high BMI may be related to the progression of COVID-19 in pregnant women after delivery." (PMID 35283947, 2021). "However, protein reserves and albumin levels are within the normal range in this study, which can be attributed to albumin supplement and nutrition supply in patients with severe and critical COVID-19 after the admission to the hospital." (PMID 33832097, 2021). "Combining the correlation analysis with the reference value analysis, we found that the critical COVID-19 patients are usually accompanied by low values of lymph, eGFR, albumin and Serum Sodium, high values of LDH, hs-CRP, indirect bilirubin, creatinine and INR." (PMID 33557818, 2021). "Moreover, we also identified albumin as an independent risk factor for pulmonary fibrosis, which emphasized the importance of correcting albumin abnormalities in patients with COVID-19." (PMID 33755708, 2021). "Furthermore, urinary SARS-CoV-2 N and plasma albumin levels at ICU admission equally allowed for a robust identification of patients at risk for prolonged ICU length of stay and premature death in COVID-19." (PMID 34113632, 2021). "Complementary to previous reports on biomarkers measured during COVID-19, we observed lower levels of a priori measurements of albumin, hemoglobin, calcium, HDL cholesterol, lymphocyte proportion, and lymphocyte to leukocyte ratio more frequently in deceased patients." (PMID 35602191, 2021). "Lower albumin levels may be a warning sign of the need for intense follow-up after delivery in a patient with COVID-19." (PMID 35283947, 2021). "The increased ALT, AST, TBIL, ALP, GGT, and decreased albumin on admission had a non-linear positive association with the risk of death, which was homogeneous across the severity of COVID-19." (PMID 34179034, 2021). "Interestingly, albumin supplementation in COVID-19 patients produced a reduction in D-dimer levels and a decrease in overall mortality with a trend toward fewer thromboembolic events." (PMID 34441957, 2021).
COVID-19 (continued). "Although albumin measurement appears to be easier than IL-15 quantification in primary care, IL-15 serum levels can be detected quickly and affordably in tertiary healthcare centers, where most patients with severe COVID-19 are admitted." (PMID 34683480, 2021). "However, we should further explore the exact molecular mechanism through which albumin and IL-15 worsen survival prognosis in COVID-19." (PMID 34683480, 2021). "In serum chemistries COVID-19 patients had lower albumin level (2.80 [2.40–3.23] vs 3.50 [2.90, 3.90]; p < 0.001), alanine aminotransferase (ALT) (20 vs 30; p < 0.039), aspartate aminotransferase(AST) (24 vs 39; p < 0.001) and lactate (0.96 [0.76–1.25] vs 1.30 [1.00, 1.70]; p < 0.001)." (PMID 34131192, 2021). "The explanatory variables for COVID-19 severity were the body mass index (BMI), hemoglobin, albumin, 3-Hydroxyisovaleric acid, CD8+ effector memory T cells, Th1 cells, low-density granulocytes, monocyte chemoattractant protein-1, plasma TRIM63, and circulating neutrophil extracellular traps." (PMID 34566957, 2021). "As a vital inverse acute phase reactant, serum albumin could maintain plasma redox state and protect against the cytokine storm and organ failure, which are often observed in severe COVID-19 patients." (PMID 34122505, 2021). "Similar to baseline LFTs abnormality, abnormal LFTs during hospitalization, peak AST, TBIL, ALP, GGT, and nadir albumin but not peak ALT were significantly (or a trend toward) associated with adverse outcomes of COVID-19." (PMID 34179034, 2021). "The reduced albumin may be related to the progression of the disease particularly in severe and critically ill COVID-19 patients." (PMID 34287285, 2021). "Besides, there are limited studies that have reported low albumin levels in COVID-19 patients with severe illness as well as cholestatic liver biomarkers such as GGT and ALP, which are usually deranged in persons with severe disease." (PMID 34287285, 2021). "We thus investigated whether the use of the IL-15-to-albumin ratio enables improving mortality prediction at hospital admission in a large group of COVID-19 patients." (PMID 34683480, 2021). "Considering this, the observed findings of lowered serum free thiol concentrations among subjects with COVID-19 may (at least partially) be explained by their significantly lower albumin concentrations." (PMID 34943125, 2021). "Recently, a panel of five proteins with downregulated expression, namely, albumin (ALB), apolipoprotein A1 (APOA1), apolipoprotein C1 (APOC1), gelsolin (GSN), and transferrin (TF), was identified as a core signature associated with the severity of COVID-19." (PMID 34471261, 2021). "In parallel, a study conducted in a large group of COVID-19 patients reported that the blood urea nitrogen-to-albumin ratio (BAR) could predict mortality with an AUROC of 0.809." (PMID 34683480, 2021). "The low molecular weight fraction of human serum albumin (LMWF5A) is a novel biologic drug that is currently under clinical investigation for the treatment of osteoarthritis and the hyper-inflammatory response associated with COVID-19." (PMID 33256749, 2020). "LDH, ALP, GGT, TBiL, prealbumin, and albumin may be helpful for evaluating and predicting disease prognosis due to their correlation with disease severity in COVID-19." (PMID 33521010, 2020). "Hence, comorbidity, ALB, CRP, and age ≥60 years were identified as the most influential risk factors for the severity of COVID-19 in these patients." (PMID 33330318, 2020). "Based upon our results and the clinical experience about COVID-19, we conjectured that the decrease of albumin may be related to the low nutritional status, hypo-function of liver synthesis and acute kidney injury after SARS-CoV-2 infection." (PMID 33110593, 2020).
COVID-19 (continued). "In summary, we elaborated the clinical features and virological transformation course of COVID-19, identified several independent early predictors (age, lymphocyte count, albumin, NLR), and constructed a prediction model with a favorable predictive efficacy for severe COVID-19." (PMID 33110593, 2020). "However, addition of the lymphocyte count to the serum level of albumin improved the prediction of COVID-19 severity (NRI = 0.4848, 95%CI: 0.1094–0.8604, P = 0.011; IDI = 0.0464, 95%CI: 0.0086–0.0844, P = 0.016)." (PMID 33521032, 2020). "Although benefits from albumin administration are controversial, future research should determine whether this treatment might be useful in COVID-19, especially in those elderly patients who tend to have lower albumin levels ⁠." (PMID 32899640, 2020). "In addition, serum albumin levels in COVID-19 were usually very low (in severe forms is usually < 3.1 g/dL), raising the possibility of a negative correlation between albumin concentration in plasma and increase of the RAS activity." (PMID 32708755, 2020). "ALB has been reported to be negatively correlated with the severity of COVID-19." (PMID 33170150, 2020). "Patients with COVID-19 often demonstrated decreased levels of serum total protein (TP) and albumin." (PMID 33376750, 2020). "- Comorbidity, ALB, CRP, and age ≥60 years are independent risk factors for severe COVID-19." (PMID 33330318, 2020). "With following parameters such as age > 52 years, C-reactive protein > 64.79 mg/L, lactate dehydrogenase > 245 U/L, D-dimer > 0.96 μg/mL, serum amyloid A > 100.02 mg/L, or albumin < 36 g/L, the progress of COVID-19 to critical stage should be closely observed and possibly prevented." (PMID 32677918, 2020). "Age; temperature; anorexia; and white blood cell count, neutrophil percentage, platelet count, lymphocyte count, C-reactive protein, aspartate transaminase, creatine kinase, albumin, and fibrinogen values were significantly different between patients with mild and severe COVID-19 (P < 0.05)." (PMID 32571410, 2020). "Liver involvement present with the elevation of enzymatic levels of alanine transaminase (ALT), aspartate transaminase (AST), alkaline phosphatase (ALP), and gamma-glutamyl transferase (GGT) accompanied by enhanced total bilirubin and decreased albumin levels has been reported in COVID-19 cases." (PMID 32754608, 2020). "With the following parameters such as age > 52 years, C-reactive protein > 64.79 mg/L, lactate dehydrogenase > 245 U/L, D-dimer > 0.96 μg/mL, serum amyloid A > 100.02 mg/L, or albumin < 36 g/L, the progress of COVID-19 to critical stage should be closely observed and possibly prevented." (PMID 32677918, 2020). "In addition, several previous studies have shown that patients with COVID-19 were often accompanied by albumin reduction, and the level of serum albumin in severe patients were lower than that in mild." (PMID 33110593, 2020). "Furthermore, the HD patients have higher expression of BUN, Cr, BNP, uric acid, and lower expression of ALB than the previous reported common population with COVID-19." (PMID 32722980, 2020). "Theoretically, in view of the decrease in the number of lymphocytes and their subsets in the early stage of the disease and the poor immune function potentially caused by various complications, ALB and PAB are potential and feasible predictors for the prognosis of COVID-19." (PMID 32671085, 2020). "Thus, the additive effect of both albumin and globulin would not only be a prognostic factor for potential COVID-19 complications during the course of the illness, but also an initial risk index of SARS-CoV-2 positive individuals." (PMID 33224959, 2020). "In this study, using logistic regression with least absolute shrinkage and selection operator (LASSO) regularization, we found that albumin (ALB), d-dimer and onset to hospitalization (OH) time were significant predictors for the severity of COVID-19 in elderly patients." (PMID 33170150, 2020).